EGFR (epidermal growth factor receptor)
Diseases named in the same sentence as EGFR in open-access papers (continued):
Sharing a sentence is not in itself a finding about the gene and the disease.
lung adenocarcinoma (continued). "They identified 17 microRNAs that were differentially expressed between EGFR-mutated and EGFR-wild-type lung adenocarcinomas, and 3 microRNAs differentially expressed between KRAS-mutated and KRAS-wild-type lung adenocarcinomas." (PMID 28486396, 2017). "In our study, 12% of lung adenocarcinomas carried an EGFR mutation, a prevalence in line with literature data in Caucasian populations.." (PMID 28427238, 2017). "Of the 734 lung adenocarcinomas, EGFR and KRAS mutations were detected in 334 (46%) and 83 (11%), respectively." (PMID 28422979, 2017). "Pathologically, EGFR-mutated lung adenocarcinomas typically show nuclear TTF-1 (NKX2-1) immunostaining and a hobnail cell type." (PMID 28894699, 2017). "Epidermal growth factor receptor (EGFR) mutations occur in about 40% to 50% of lung adenocarcinoma patients of East Asian descent." (PMID 28212572, 2017). "CT imaging features of lung adenocarcinomas in combination with clinical variables can be used to prognosticate EGFR mutation subtypes." (PMID 28336963, 2017). "In approximately one third of our cases the calculated percentage of mutated neoplastic cells was above 100%, most likely reflecting the well-known occurrence of amplification of mutated EGFR alleles in lung adenocarcinoma." (PMID 28520821, 2017). "Here, we report that CAFs isolated from a lung adenocarcinoma patient intensified the antitumor effect of gefitinib on EGFR mutation-positive lung adenocarcinoma cells." (PMID 28429795, 2017). "EGFR-mutated lung adenocarcinomas with secondary resistance to tyrosine kinase inhibitors exhibit in approximately 60% a secondary T790M EGFR mutation." (PMID 28367253, 2017). "For example, KRAS mutations are frequently detected in lung adenocarcinomas in smokers, whereas genetic alterations in EGFR, ALK, ROS1, and RET are frequently detected in lung adenocarcinomas in non-smokers." (PMID 28894699, 2017). "The molecular target therapy has been developed for lung adenocarcinoma patients harboring EGFR gene mutation." (PMID 29383112, 2017). "Previous studies have identified several unique miRNA expression profiles related to EGFR mutational status and sensitivity to EGFR TKIs in lung adenocarcinoma tissues." (PMID 29383112, 2017). "Since p-stage I lung adenocarcinoma incidence is significantly increased in patients with EGFR mutation, it is critical to select an appropriate surgical procedure, especially that with significant effects on the incision margin and recurrence." (PMID 28253871, 2017). "As an irreversible inhibitor of the ErbB family of tyrosine kinases, the second-generation TKIs afatinib is a valuable option for patients with advanced lung adenocarcinoma harboring activating EGFR mutations." (PMID 28676644, 2017). "PD-L1 positivity in lung adenocarcinoma has been associated with higher mortality and EGFR wild-type status." (PMID 28486396, 2017). "MiR-145 is down-regulation in NSCLC and the restoration of miR-145 expression remarkably suppresses the growth of lung adenocarcinoma cells with EGFR mutation." (PMID 28445945, 2017). "EGFR-TKIs have become the standard first-line therapy for advanced lung adenocarcinoma patients with EGFR mutations." (PMID 28445978, 2017). "For example, CNGs of EGFR, HER2, HER3, and HER4 had strongly associations with poor overall survival in lung adenocarcinoma with EGFR-activating mutations." (PMID 29190914, 2017). "Tyrosine kinase inhibitors (TKIs) are widely used to treat lung adenocarcinoma patients with EGFR mutations or ALK-fusions." (PMID 29285248, 2017). "Twenty-one surgical samples of lung adenocarcinoma were used, of which 7 contained EGFR exon 19 mutation, 7 contained EGFR exon 21 mutation (p.L858R) and 7 were EGFR wild-type." (PMID 28288198, 2017). "Although lung adenocarcinoma patients with EGFR mutations benefit from TKI treatment, they acquire drug resistance after approximately 9 months." (PMID 29163769, 2017).
lung adenocarcinoma (continued). "In public dataset GSE31210, low FSTL1 RNA level was associated with lung adenocarcinoma patients with ALK-fusion or KRAS mutation compared to those with EGFR mutation or EGFR/KRAS/ALK triple-negative tumors." (PMID 28852126, 2017). "In conclusion, in this explorative study, we identified circulating miRNA signature with significantly different expression associated with EGFR gene mutational status in Japanese smoker males with lung adenocarcinoma." (PMID 29383112, 2017). "The use of tyrosine kinase inhibitors (TKIs), such as gefitinib and erlotinib, in EGFR-mutant lung adenocarcinoma patients successfully causes tumor regression and prolonged patient survival; however, drug resistance and tumor relapse eventually occur." (PMID 29163769, 2017). "Taken together, autophagy plays a cytoprotective role in afatinib therapy and the inhibition of autophagy shows an increased sensitivity of lung adenocarcinoma cells harboring activating EGFR mutations to afatinib." (PMID 28676644, 2017). "LUX-Lung 3 trial was a global, randomized study which evaluated the efficacy and safety between afatinib and chemotherapy as a first-line treatment in patients with proven EGFR mutation and lung adenocarcinoma histologically." (PMID 29088904, 2017). "In this study, we found that the probability of EGFR mutation in lung adenocarcinoma was inversely correlated with SUVmax." (PMID 28422979, 2017). "In this study, we evaluated the performance of a novel assay called ADx-SuperARMS in detecting EGFR mutations in plasma cell-free DNA from patients with advanced lung adenocarcinoma." (PMID 28829813, 2017). "In lung adenocarcinoma, EGFR and Ras mutations have been frequently detected as drivers in tumorigenesis." (PMID 28090355, 2017). "Subgroup analysis from LUX-LUNG 3 and LUX-LUNG 6 studies demonstrated a significant overall survival benefit for afatinib compared to chemotherapy in UICC stage IIIB/IV lung adenocarcinoma patients with 19del-EGFR mutation." (PMID 28540256, 2017). "Nevertheless, little is known about smoking history associated circulating miRNAs which can predict EGFR mutational status and prognosis of smoker males with lung adenocarcinoma." (PMID 29383112, 2017). "Among them, 158 patients with advanced lung adenocarcinoma with EGFR exon 19 deletion mutations received EGFR-TKIs." (PMID 29340050, 2017). "In lung adenocarcinoma, higher expression of B7-H3 has been associated with EGFR wild-type and smoking patients." (PMID 28486396, 2017). "Compared with early resectable lung adenocarcinoma patients harboring wild-type EGFR, those with EGFR mutation showed a higher rate of local invasion, with pleural invasion most common." (PMID 28253871, 2017). "Afatinib has also proven to be effective as a first-line therapy in patients with advanced EGFR mutation-positive lung adenocarcinoma in the LUX-Lung 3 and LUX-Lung 6 trials." (PMID 29163842, 2017). "The purpose of this study was to investigate the status of Rb in lung adenocarcinoma patients with EGFR mutations and define the clinicopathologic features." (PMID 28532538, 2017). "For decades, mutations in KRAS and EGFR have been recognized to play a critical role in lung adenocarcinoma and have been used to classify these tumors into subtypes based on mutation status." (PMID 29322935, 2017). "In the present study, we retrospectively investigated the clinicopathologic characteristics and prognosis of patients with activating EGFR exon mutations in a large cohort of patients with lung adenocarcinoma." (PMID 28380449, 2017). "Smoking was associated with lower incidence of EGFR mutation rate and reduced OS of advanced lung adenocarcinoma patients in a dose-dependent manner." (PMID 29228697, 2017). "The TMA slides, obtained from the University of Pittsburgh Lung Specialized Program of Research Excellence (SPORE) and constructed using randomly selected archival lung adenocarcinomas with known EGFR and KRAS mutation status, were stained for MAP4K4." (PMID 28306189, 2017).
lung adenocarcinoma (continued). "All these data illustrate that autophagy has a protective function against the afatinib-triggered cytotoxicity and apoptosis, and autophagy inhibition can improve the anti-cancer effect of afatinib in lung adenocarcinoma cells with activating EGFR mutations." (PMID 28676644, 2017). "In Europe, except for Spain, the frequency of EGFR mutations is the lowest reported, in approximately 10% of metastatic or advanced lung adenocarcinomas." (PMID 28881604, 2017). "Epidermal growth factor receptor (EGFR) mutations are found in lung adenocarcinomas leading to tumor cells proliferation and survival." (PMID 29163769, 2017). "We further tested the value of histologic grade as a predictive factor of the incidence of EGFR mutations in female patients with lung adenocarcinoma." (PMID 29232915, 2017). "BMXΔN is not found in paired pathologically normal lungs and positively correlated with EGFR mutation in lung adenocarcinomas." (PMID 28422715, 2017). "In this study, afatinib was administered as a first-line therapy to stage IIIB/IV lung adenocarcinoma patients harboring EGFR mutations." (PMID 29228636, 2017). "In the human lung adenocarcinoma tissue sample analysis, a correlation between EGFR mutation status and YAP1 expression was detected." (PMID 29163769, 2017). "Epidermal growth factor receptor tyrosine kinase inhibitors (EGFR-TKIs) significantly improve the survival of advanced lung adenocarcinoma patients harboring EGFR mutation." (PMID 28935011, 2017). "This study aimed to investigate the clinicopathologic characteristics of classic EGFR exon mutation in Chinese patients with TMN stage III lung adenocarcinoma who received radical surgery." (PMID 28380449, 2017). "Tyrosine kinase inhibitors (TKIs) such as gefitinib and erlotinib are effective against lung adenocarcinomas harboring epidermal growth factor receptor (EGFR) mutations." (PMID 28422737, 2017). "The exon 19 and 21 in Epidermal Growth Factor Receptor (EGFR) mutation are the most common subtype of lung adenocarcinoma, and the strongest predictive biomarker for progression-free survival and tumor response." (PMID 28336963, 2017). "The frequencies of driver genetic alterations in Caucasians were determined in TCGA study, whereas lung adenocarcinoma in Asians is characterized by a high frequency of EGFR mutations (approximately 50%) and low frequency of KRAS mutations (approximately 10%)." (PMID 28894699, 2017). "EGFR mutations occur in greater frequency in individuals of Asian heritage, typically in lung adenocarcinomas." (PMID 29228636, 2017). "It indicates that ctDNA still has huge challenges when facing lung adenocarcinoma with EGFR mutation." (PMID 29088904, 2017). "One thousand thirteen patients with lung adenocarcinoma underwent a mutational analysis test during the study period at the Karolinska University Hospital; among them, 104 (10.3%) tested positive for a EGFR mutation, 52 (5.1%) had an ALK translocation." (PMID 28560038, 2017). "Alexander reported that patients with malignant pleural effusion of lung adenocarcinoma had increased frequency of EGFR and KRAS mutations." (PMID 28938549, 2017). "In conclusion, smoking reduced both the EGFR mutation rate and survival duration in advanced lung adenocarcinoma patients in a dose-dependent manner, particularly among those who started smoking at a young age." (PMID 29228697, 2017). "With the development of genetic mutations and targeted drugs, accurate therapy of lung adenocarcinoma attracts much more attention, and more research is focued on epidermal growth factor receptor (EGFR)." (PMID 28641695, 2017). "Approximately 30–40% of Asian patients and 10–15% of Caucasian patients with lung adenocarcinoma harbor activating mutations in the epidermal growth factor receptor (EGFR) gene." (PMID 29228562, 2017). "The current study aimed to investigate the pure prognostic role of EGFR mutations in treatment-naïve patients with resected stage I lung adenocarcinoma." (PMID 29065153, 2017).
lung adenocarcinoma (continued). "Generally, CAFs are believed to promote resistance of EGFR mutation-positive lung adenocarcinoma to EGFR-TKIs via soluble factors or direct contact, whereas the expression of these factors varies among CAFs derived from different tumors." (PMID 28429795, 2017). "A total of 48 patients with stage IV lung adenocarcinoma harboring susceptible EGFR mutations who received afatinib as their first-line therapy were enrolled." (PMID 29237484, 2017). "To assess a highly sensitive method, we evaluated the use of digital PCR in the detection of EGFR mutations in tumor tissue from 47 advanced lung adenocarcinoma patients through comparison with NGS and ARMS." (PMID 28978074, 2017). "In the present study, we investigate the role of IGF1R in acquired resistance to erlotinib in the EGFR exon19del mutated lung adenocarcinoma cell line HCC827." (PMID 28418902, 2017). "The frequency of EGFR sensitizing mutations ranges from 15% of lung adenocarcinoma in Caucasian populations to as high as 50% in Asian populations." (PMID 29312641, 2017). "A targeted therapy using tyrosine kinase inhibitors (IKTs) proved to be very effective in patients with lung adenocarcinoma and activated epidermal growth factor receptor (EGFR) mutations." (PMID 28470464, 2017). "Somatic mutations in the epidermal growth factor receptor (EGFR) gene occur in more than half cases of lung adenocarcinoma in Japan and those are associated with good responsiveness to EGFR tyrosine kinase inhibitors (TKIs), gefitinib and erlotinib." (PMID 29383112, 2017). "In Epidermal Growth Factor Receptor (EGFR)-mutated lung adenocarcinoma, we previously reported on surgical samples that TWIST1 expression was linked to EGFR mutations, low E-cadherin expression and low disease-free survival." (PMID 28771186, 2017). "Evaluation of EGFR mutation has been employed to predict lung adenocarcinoma response to EGFR kinase inhibitors in clinic." (PMID 28503151, 2017). "We also show that a serum CEA level of less than 10 ng/ml was a predictor of favorable outcomes in advanced lung adenocarcinoma patients with EGFR-sensitive mutations (exon 19 deletion and L858R)." (PMID 29050327, 2017). "Our study suggests that patients with lung adenocarcinoma bearing a EGFR-mutation have a decreased risk of VTE compared with patients with other forms of lung adenocarcinoma." (PMID 28560038, 2017). "EGFR-TKIs have been proved to be promising treatment of NSCLC, especially for lung adenocarcinoma patients harboring EGFR mutations." (PMID 29259263, 2017). "In total, 48/70 (68.6%) patients in this study diagnosed with stage III/IV adenocarcinoma of the lung had EGFR mutation testing." (PMID 28367333, 2017). "EGFR-TKIs show dramatic treatment benefits for advanced lung adenocarcinoma patients with activating EGFR mutations." (PMID 29259263, 2017). "In recent years, it has been reported that the incidence of epidermal growth factor receptor (EGFR) mutations in the bone metastases was high in the lung adenocarcinoma." (PMID 28061855, 2017). "This is the first study suggesting the diagnostic value of these miRNA as potential biomarkers whose alteration would be able to distinguish EGFR gene mutation status of male smoker patients with early stage lung adenocarcinoma." (PMID 29383112, 2017). "In a retrospective trial of 314 lung adenocarcinoma patients with EGFR mutations, the multivariate model analysis showed a strong association between EGFR mutation status and brain metastasis (adjusted odds ratio = 3.83, 95% CI: 1.72-8.55, P = 0.001)." (PMID 28376735, 2017). "We evaluated the real-world efficacy and side effects of afatinib as a first-line therapy for advanced EGFR mutation-positive lung adenocarcinoma." (PMID 29163842, 2017). "In this paper we performed an accurate literature review and we reported two new cases of patients diagnosed with lung adenocarcinoma, exhibiting both EGFR mutation and EML4-ALK rearrangement." (PMID 28938691, 2017).